SLC5A2 (solute carrier family 5 member 2)
Description:
Electrogenic Na(+)-coupled sugar symporter that actively transports D-glucose at the plasma membrane, with a Na(+) to sugar coupling ratio of 1:1. Transporter activity is driven by a transmembrane Na(+) electrochemical gradient set by the Na(+)/K(+) pump. Unlike SLC5A1/SGLT1, requires the auxiliary protein PDZK1IP1/MAP17 for full transporter activity. Has a primary role in D-glucose reabsorption from glomerular filtrate across the brush border of the early proximal tubules of the kidney (By similarity).
Synonyms: SGLT2
Tractability: Small molecule: an approved drug acts on it; a structure with a bound ligand is known; a high-quality ligand is known; it belongs to a druggable protein family. Antibody: UniProt places it where antibodies can reach, with high confidence; its Gene Ontology location is reachable by antibodies, with high confidence; UniProt predicts a signal peptide or a membrane-spanning region. PROTAC: a small molecule that binds it is known.
Target class: SLC superfamily of solute carriers; SLC05 family of sodium-dependent glucose transporters; Electrochemical transporter; Transporter
Chemical probes: CHEMBL1762505, CHEMBL496138, ERTUGLIFLOZIN (high quality)
Gene: Protein-coding gene on chromosome 16 (31,483,002 to 31,490,860, forward strand). Ensembl gene ENSG00000140675.
Subcellular location: Apical cell membrane
Pathways (Reactome):
Disease: Defective SLC5A2 causes renal glucosuria (GLYS1)
Transport of small molecules: Cellular hexose transport
Gene Ontology:
Molecular function: alpha-glucoside transmembrane transporter activity; D-glucose transmembrane transporter activity; D-glucose:sodium symporter activity; protein binding; low-affinity D-glucose:sodium symporter activity; solute:sodium symporter activity; transmembrane transporter activity
Biological process: alpha-glucoside transport; D-glucose import across plasma membrane; sodium ion import across plasma membrane; carbohydrate metabolic process; hexose transmembrane transport; renal D-glucose absorption; D-glucose transmembrane transport; transmembrane transport
Cellular component: extracellular exosome; plasma membrane; transmembrane transporter complex; apical plasma membrane; membrane
Genetic constraint (gnomAD): Loss-of-function variants: 69 observed, 69.67 expected, observed/expected ratio (o/e) 0.99, 90% interval 0.81 to 1.21. The upper end of that interval is the gene's LOEUF score, 1.21, which puts it in group 5 of 6, group 1 being the genes least tolerant of losing a copy. Missense variants: 1,001 observed, 939.97 expected, observed/expected ratio (o/e) 1.06, 90% interval 1.01 to 1.12. Synonymous variants: 455 observed, 397.87 expected, observed/expected ratio (o/e) 1.14, 90% interval 1.06 to 1.24.
Homologues: Orthologues: chimpanzee SLC5A2 (99% identical), macaque SLC5A2 (98% identical), guinea pig SLC5A2 (91% identical), rat Slc5a2 (91% identical), mouse Slc5a2 (91% identical), pig SLC5A2 (88% identical), rabbit SLC5A2 (85% identical), zebrafish slc5a2 (69% identical), tropical clawed frog slc5a2 (65% identical), Drosophila melanogaster bumpel (17% identical), Drosophila melanogaster rumpel (16% identical), Drosophila melanogaster CG31668 (16% identical), and 9 more. Paralogues in human: SLC5A1 (58% identical), SLC5A4 (55% identical), SLC5A9 (53% identical), SLC5A10 (49% identical), SLC5A11 (49% identical), SLC5A3 (45% identical), SLC5A12 (21% identical), SLC5A5 (20% identical), SLC5A8 (20% identical), SLC5A6 (19% identical), SLC5A7 (17% identical).
Diseases named in the same sentence as SLC5A2 in open-access papers:
SLC5A2 is named in the same sentence as 593 diseases in open-access papers, as found by Europe PMC text mining. Sharing a sentence is not in itself a finding about the gene and the disease. The quoted sentences say what the papers report.
diabetes (2,321 papers, 2012 to 2026). "The gene SLC5A2, which is implicated in both diabetes and gangrene, serves as the specific target for SGLT2 inhibitors in diabetic therapy." (PMID 40657379, 2025). "Previous studies suggested SLC5A2 genetic variants were associated with urinary glucose excretion, glucose homeostasis, and diabetes." (PMID 34440348, 2021). "To investigate the interaction effect of SLC5A2 SNPs and diabetes on the cardiovascular risk we conducted tests for interaction and performed subgroup analyses with respect to the presence or absence of T2DM." (PMID 30988077, 2019). "It is noteworthy that among those FRG cases, only four cases (2.9%) had diabetes, suggesting that SLC5A2 gene mutation might be protective to diabetes." (PMID 35229480, 2022). "Whether SLC5A2 SNPs in a pure diabetes cohort are associated with microvascular diabetes complications is an important question that should be addressed in large cohorts of patients with diabetes." (PMID 30988077, 2019). "In addition, we performed a meta-analysis including data from earlier studies to further elucidate the impact of genetic variants of the SLC5A2 gene on the presence of diabetes." (PMID 30988077, 2019). "Theoretically, the SLC5A2 gene mutation carriers might have lower risk for developing diabetes." (PMID 35229480, 2022). "Drugs targeting SGLT2 (SLC5A2), i.e., gliflozins (canagliflozin, empagliflozin, and dapagliflozin), are used in the treatment of diabetes mellitus." (PMID 33919957, 2021). "Researchers demonstrated that elevated HNF-1α expression and binding activity in the solute carrier family 5-member 2 promoter leads to the diabetes-induced overexpression of SGLT2." (PMID 33187206, 2020). "Given that loss-of-function SLC5A2 variants cause glucosuria and pharmacologic induction of glucosuria via SGLT2 inhibition is used to treat diabetes, we hypothesized that SLC5A2 variants will reduce the risk of diabetes." (PMID 39412882, 2025). "Common genetic variants in the SLC5A2 gene neither affect diabetes-related metabolic profiles nor response to SGLT2 inhibitor therapy." (PMID 35614469, 2022). "Although research into FRG may help with a breakthrough for diabetes treatment, expression and functional studies of SLC5A2 mutations in FRG are rare, and the role of SGLT2 C-terminal mutations needs further clarification." (PMID 27000029, 2016). "The genetics of renal glucosuria is poorly understood, and even less is known on how loss-of-function variants in SLC5A2 may affect response to SGLT2 inhibitors, a new class of medication gaining popularity to treat diabetes by artificially inducing glucosuria." (PMID 39412882, 2025). "However, for some of these genes such as SLC5A2 (encoding SGLT2) we do not detect associations with diabetes traits despite having a reasonable number of variant carriers." (PMID 34732801, 2021). "Sglt1 (also known as Slc5a1) and Sglt2 (also known as Slc5a2) knockout mice were employed to develop sotagliflozin, a dual SGLT1/SGLT2 inhibitor having success in clinical trials for diabetes." (PMID 31064765, 2019). "Furthermore, MIDY pigs provide an interesting model for testing if diabetes treatments, e.g. insulin replacement therapies or SGLT2 (also known as SLC5A2) inhibitors, can revert the observed pulmonary alterations." (PMID 38900131, 2024). "Co-treatment substantially reduced the diabetes-induced upregulation of Slc2a2, but not Slc5a1 and Slc5a2, mRNA levels when compared to all other diabetic arms." (PMID 27226136, 2016). "Moreover, modulation of the Slc5a2 activity by inhibitors (SGLT2 inhibitors), which are promising drugs in the treatment of diabetes, including diabetic nephropathy, may also modulate cyst growth in polycystic kidney diseases." (PMID 35252349, 2022). "The SGLT2 inhibitors are originally designed for diabetes, which targets the SLC5A2 gene, and have shown benefit for HF, regardless of whether comorbid with diabetes or not." (PMID 34026868, 2021).
type 2 diabetes (1,922 papers, 2012 to 2026). "In a large study of 2229 subjects at increased risk for type 2 diabetes the impact of common SLC5A2 variants (rs9934336, rs9924771, rs3813008 and rs3116150) on empagliflozin response was analyzed." (PMID 32961860, 2020). "We investigated if common SLC5A2 rs9934336 polymorphism influences glycemic control and risk for macro or microvascular complications in Slovenian type 2 diabetes (T2D) patients." (PMID 33269015, 2020). "The present study, therefore, aimed to investigate SLC5A2 single nucleotide polymorphisms (SNPs) in relation to type 2 diabetes and coronary artery disease (CAD) and prospectively the incidence of cardiovascular events." (PMID 30988077, 2019). "Targeting SLCs has already been successful, for example, in the treatment of type-2 diabetes by inhibiting SLC5A2 (SGLT2), a sodium-dependent glucose transporter responsible for glucose reabsorption in the kidney." (PMID 40355754, 2025). "Invokana (inhibitor of Slc5a2) has been used for blood glucose management to alleviate kidney injury in type 2 diabetes patients." (PMID 37686311, 2023). "Genetic variants associated with glycated hemoglobin (HbA1c), Type 2 Diabetes (T2D), and antidiabetic drug targets (KCNJ11, ABCC8, PPARG, INSR, GLP1R, SLC5A2, and DPP4) were sourced from genome-wide association studies in the UK Biobank and the DIAMANTE consortium." (PMID 39640975, 2024). "The aim of our study was to investigate if common polymorphism SLC5A2 rs9934336 influences blood glucose levels and risk for macro and microvascular complications in Slovenian Type 2 diabetes patients even in the absence of treatment with SGLT2 inhibitors." (PMID 33269015, 2020). "A study population of 375 healthy subjects at increased risk for type-2 diabetes, phenotyped by a 5-point oral glucose tolerance test (OGTT) and genotyped for recently described SLC5A2 tagging single nucleotide polymorphisms (SNPs), was selected for plasma glucagon measurements." (PMID 28472182, 2017). "In a very recent announcement, dapaglifloxin (Forxiga), the first of a class of inhibitors of the SGLT2 (SLC5A2) sugar transporters, has been approved in Europe for treatment of Type 2 diabetes." (PMID 23506860, 2013).
heart failure (1,474 papers, 2016 to 2026). Inability of the heart to pump blood at an adequate rate to meet tissue metabolic requirements. "Sodium/glucose transporter 2 (SGLT2 or SLC5A2) inhibitors lower blood glucose and are also approved treatments for heart failure independent of raised glucose." (PMID 39056245, 2024).
Hyperglycemia (372 papers, 2012 to 2026). An increased concentration of glucose in the blood. "As a consequence, carriers of HNF1A mutations show glycosuria that begins several years before hyperglycemia and is likely due to down regulation of SLC5A2 which encodes SGLT2, a sodium-dependent glucose transporter known to play a major role in renal glucose reabsorption." (PMID 35052457, 2022). "Two genes are targets of drugs approved for treatment of hyperglycemia: alpha glucosidase (GAA), targeted by miglitol, and SLC5A2 (aka SGLT2), targeted by dapagliflozin." (PMID 38199042, 2024). "SLC5A2 expression and hepatocyte nuclear factor 4-A (HNF4A), which regulates the expression of SLC5A2, decrease significantly in episodes of hyperglycemia because alpha cells become idle and do not require glucagon secretion." (PMID 36819350, 2023). "In conclusion, PRG should be considered when making a differential diagnosis of patients exhibiting unexplained renal glucosuria without hyperglycemia or hypoglycemia, and SLC5A2 gene analysis should be performed." (PMID 24255686, 2013). "Although PRG is a rare disease, many subjects with glucosuria without hyperglycemia have been confirmed by SLC5A2 gene analysis, as in the current case." (PMID 24255686, 2013). "Mutations in the SLC5A2 gene encoding SGLT2 are found in persons with familial renal glucosuria (FRG); FRG is considered a benign condition, with affected individuals exhibiting glucosuria in the absence of hyperglycemia without alteration in other proximal tubular functions." (PMID 22355316, 2012). "Since SGLTs reabsorbs approximately 90% of filtered glucose, SLC5A2 mutations may affect SGLT2 expression levels to affect the proportion of glucose reabsorption, resulting in familial renal glycosuria, which is characterized by isolated glucosuria without overt hyperglycemia." (PMID 35614469, 2022).
diabetic kidney disease (297 papers, 2013 to 2026). Progressive kidney disorder caused by vascular damage to the glomerular capillaries, in patients with diabetes mellitus. "Among various complement components and receptors, the only significant finding was a positive association between SLC5A2 and the tubulointerstitial synthesis of the complement component C5 in diabetic nephropathy (p = 0.0109)." (PMID 38069385, 2023). "We next analyzed the relevance of tubulointerstitial SLC5A2 mRNA expression in association with the identified synthesis of distinct complement components, specifically in diabetic nephropathy." (PMID 38069385, 2023). "Because we found a predominant tubulointerstitial expression of SLC5A2 in both healthy controls and diabetic nephropathy, we next analyzed the association between tubulointerstitial SLC5A2 mRNA expression levels, focusing on various complement components and receptors." (PMID 38069385, 2023). "Publicly available datasets for SLC5A2 (encoding SGLT-2) and complement system components were extracted specifically from microdissected tubulointerstitial (healthy controls: n = 31, diabetic nephropathy: n = 17) and glomerular compartments (healthy controls: n = 21, diabetic nephropathy: n = 12)." (PMID 38069385, 2023). "First, we compared tubulointerstitial and glomerular log2 SLC5A2 mRNA expression levels and confirmed a predominant synthesis within the tubulointerstitial compartment in healthy controls and diabetic nephropathy." (PMID 38069385, 2023). "Interestingly, we identified decreased SLC5A2 mRNA expression in diabetic nephropathy as compared to healthy controls." (PMID 38069385, 2023).
Hypoglycemia (255 papers, 2013 to 2026). A decreased concentration of glucose in the blood. "Hypoglycemia is the most important risk in T1DM patients with SLC5A2 mutation (by acting as an SGLT2 inhibitor), especially in those <5 years of age, contrary to the studies of Fattah, Evans, and Wolfs Dorf." (PMID 38923174, 2024). "One individual, who was compound heterozygous for mutations in the SLC5A2 gene suffered from severe urogenital candida infections and postprandial hypoglycemia." (PMID 26735923, 2016). "Compound heterozygosity of mutations in the SLC5A2 gene was associated with a severe form of the disease characterized by chronic urogenital candida infections and postprandial hypoglycemia." (PMID 26735923, 2016). "The KH patient with a SLC5A2 mutation presented hypoglycemia with intermittent glucosuria, suggesting that FRG may cause KH in infancy." (PMID 35422763, 2022).
Obesity (238 papers, 2013 to 2026). Accumulation of substantial excess body fat. "The mEC1 population showed an obesity-induced downregulation of transporters of major ions (Slc34a1, Slc4a4, Slc22a8, Slc13a1, Slc22a18 and Slc5a12), neutral amino acids (Slc6a19) and glucose (Slc5a2)." (PMID 36400935, 2022).
Hypertension (208 papers, 2013 to 2026). The presence of chronic increased pressure in the systemic arterial system. "Human genetic data further support the role of SGLT2 in BP regulation, with SLC5A2 polymorphisms associated with salt sensitivity, BP variability, and incident hypertension." (PMID 41596241, 2026).
Hepatic steatosis (100 papers, 2014 to 2026). Steatosis is a term used to denote lipid accumulation within hepatocytes. "Considering low expression levels of SGLT2 (Slc5a2) in the liver and cellular component of the liver, CANA is unlikely to have direct effects on these cells to attenuate either hepatic steatosis or the subsequent pathologic changes." (PMID 29402900, 2018).
atrial fibrillation (95 papers, 2018 to 2026). A disorder characterized by an electrocardiographic finding of a supraventricular arrhythmia characterized by the replacement of consistent P waves by rapid oscillations or fibrillatory waves that vary in size, shape and timing and are accompanied by an irregular ventricular response. "Mendelian randomization analyses suggest that genetic proxies for antidiabetic drug targets—KCNJ11/ABCC8, SLC5A2, and RXRB—reduce the risk of paroxysmal tachycardia (PT), right bundle branch block (RBBB), and atrial fibrillation (AF), respectively." (PMID 41357784, 2025).
glucosuria (95 papers, 2007 to 2026). "Although our association results suggest that there are numerous variants that contribute to renal glucosuria, our understanding of the genetic effects of SLC5A2 remain incomplete." (PMID 39412882, 2025). "To better characterize the genetics of renal glucosuria and its pharmacogenetic impact on antidiabetic medications designed to induce glucosuria, we evaluated SLC5A2 genetics in two large biobanks linked to electronic health record (EHR) data." (PMID 39412882, 2025). "The KH patient with a heterozygous SLC5A2 mutation had intermittent glucosuria, rapid clearance of glucose and drastically increased fasting p-GLP1 as additional features, suggesting KH in infancy as a novel manifestation of FRG." (PMID 33849624, 2021). "In humans, mild glucosuria (<10 g/1.73 m2/24 h) tends to be associated with heterozygous SLC5A2, while severe glucosuria (≥10 g/1.73 m2/24 h) is experienced by individuals with homozygosity or compound heterozygosity for SGLT2 mutations." (PMID 34948317, 2021). "Two out of three patients with renal glycosuria showed variants of uncertain significance in SLC5A2; hypercalciuric patients, as well as patients with CAKUT were all unsolved." (PMID 33964006, 2021). "Consistent with previous research, six individuals were heterozygous for SLC5A2 variants resulting in mild glucosuria (< 10 g/d), and one compound heterozygous patient from Family II had severe renal glucosuria (37.6 g/d) in the current study." (PMID 32111189, 2020). "In conclusion, we identified a genetic association with self-reported glycosuria during pregnancy, with the lead SNP located 15kB upstream of SLC5A2, a target of antidiabetic drugs." (PMID 32227112, 2020). "Developmental delay and movement abnormalities have also been reported in patients with renal glycosuria and SLC5A2 mutations." (PMID 31969655, 2020). "In our study a novel frame shift deletion (c.300-303+2del) spanning the end of exon 3 and part of the splice site in intron 3 of the SLC5A2 gene was found to be associated with glycosuria." (PMID 26735923, 2016). "Here we present data on a large pedigree with renal glycosuria due to two mutations (c.300-303+2del and p.A343V) in the SLC5A2 gene." (PMID 26735923, 2016). "The gene encoding SGLT2 is SLC5A2 and a mutation in this gene leads to glucosuria." (PMID 38298219, 2024). "We reviewed 139 cases with hereditary renal glycosuria and SLC5A2 gene mutation." (PMID 35229480, 2022). "Here, we describe ten patients with glucosuria of variable severity and nine SLC5A2 mutations." (PMID 32111189, 2020). "We speculate that glucosuria caused by carrying the SLC5A2 gene mutation may have a potentially beneficial effect on the healthy state." (PMID 24255686, 2013). "We therefore hypothesized that additional variants in SLC5A2 may cause renal glucosuria." (PMID 39412882, 2025). "Thus, mutations in the SLC5A2 gene are responsible for renal glucosuria." (PMID 30558067, 2018). "The heterozygosity of SLC5A2 mutations, no matter what kind of mutation (such as nonsense, splice-site, and missense mutations), can lead to mild glucosuria." (PMID 32111189, 2020). "Therefore, the autoantibody to SGLT2 may be a nongenetic factor of the mild to moderate glucosuria in this patient with a heterozygous mutation in SLC5A2." (PMID 30558067, 2018). "Mutations in the SLC5A2 gene are recently found to be responsible for the inherited renal glucosuria, while undifferentiated connective tissue disease (UCTD) was not considered pathogenic for renal glucosuria." (PMID 30558067, 2018).